PRMT5 (protein arginine methyltransferase 5)
Diseases named in the same sentence as PRMT5 in open-access papers (continued):
Sharing a sentence is not in itself a finding about the gene and the disease.
atherosclerosis (4 papers, 2021 to 2025). A disease characterized by the build-up of fatty material and calcium deposition in the arterial wall resulting in partial or complete occlusion of the arterial lumen. "We therefore hypothesize that a potential causal relationship may exist between PRMT5 activity, inflammation, and atherosclerosis development." (PMID 36946061, 2023). "In the current study, we have tested, in a preclinical experimental setting, whether a causal relationship exists between PRMT5 activity and atherosclerosis development." (PMID 36946061, 2023). "For example, a recent study revealed that H3R8dime and H4R3dime induced by protein arginine methyltransferase 5 (PRMT5), which was up-regulated, are associated with VSMC phenotype switching during atherosclerosis." (PMID 40102393, 2025). "Given the important role of inflammation and metabolism in atherosclerotic cardiovascular disease, here we examined the role of PRMT5 in atherosclerosis using the specific PRMT5 inhibitor GSK3326595." (PMID 36946061, 2023). "For example, the high expression of C-X-C motif chemokine ligand 10 (CXCL10), a chemokine that extensively contributes to atherosclerosis and coronary artery disease in endothelial cells, is driven in part by PRMT5 methylation of NF-κB at R30 and R35." (PMID 34685445, 2021). "Quantification of total Oil red O‐positive areas revealed that PRMT5 inhibition did not significantly change the atherosclerosis susceptibility." (PMID 36946061, 2023). "PRMT5 inhibition by low‐dose GSK3326595 treatment does not affect the inflammatory state or atherosclerosis susceptibility of Western‐type diet‐fed LDL receptor knockout mice, while it induces hepatic triglyceride accumulation." (PMID 36946061, 2023). "SIRT7-mediated succinylation of protein arginine methyltransferase 5 (PRMT5) enhances its activity and induces arginine methylation of SREBP1a, which promotes the biogenesis of fatty acids, TAGs, and cholesterol, which is strongly associated with atherosclerosis." (PMID 40710369, 2025). "As IFN‐gamma is highly expressed in atherosclerotic lesions and has emerged as a significant factor in atherogenesis, we hypothesized that PRMT5 inhibition would result in an augmented immune response and increased atherosclerosis development in our atherosclerotic mouse model." (PMID 36946061, 2023). "A follow-up study by the same group reported that, in response to TNF-α and interferon gamma (IFN-γ), PRMT5-induced methylation of p65 at R174 increases the expression of CXCL11, another chemokine that worsens the atherosclerosis pathology." (PMID 34685445, 2021). "In conclusion, we have shown that PRMT5 inhibition by chronic low dose GSK3326595 treatment does not affect atherosclerosis development and lesion composition in Western‐type diet‐fed LDL receptor knockout mice, while it does induce hepatic triglyceride accumulation." (PMID 36946061, 2023).
carcinoid tumor (4 papers, 2013 to 2024). A slow growing neuroendocrine tumor, composed of uniform, round, or polygonal cells having monotonous, centrally located nuclei and small nucleoli, infrequent mitoses, and no necrosis. "Conversely, high nuclear PRMT5 was statistically more common in carcinoid tumors (16.5%) than in high-grade NET (7.5%), p = 0.02." (PMID 24326178, 2013). "Cytoplasmic PRMT5 was associated with high grade in both NSCLC and pulmonary NET while nuclear PRMT5 was more frequent in carcinoid tumors (p < 0.05)." (PMID 24326178, 2013). "Nuclear PRMT5 expression was associated with better outcome of all pulmonary NET; however, it was not independent of tumor type and the observed survival benefit was due to predilection of nuclear PRMT5 to carcinoid tumors exhibiting better prognosis." (PMID 24326178, 2013). "Nuclear PRMT5 was more frequent in well-differentiated tumors (carcinoid tumors) than in poorly-differentiated tumors (SCLC and LCNEC)." (PMID 24326178, 2013). "Cellular localization of PRMT5 correlated with tumor grade (differentiation), where high cytoplasmic PRMT5 was more frequent in high-grade NET (12.0%) than in carcinoid tumors (4.5%), p = 0.04." (PMID 24326178, 2013).
clear cell renal cell carcinoma (4 papers, 2019 to 2024). "SREBP1, a crucial regulator of lipid accumulation and desaturation, undergoes symmetric dimethylation by PRMT5, thereby stabilizing it in clear-cell renal cell carcinoma." (PMID 38791992, 2024). "However, PRMT5 has more than just a promoting effect in cancer, and it has been confirmed that PRMT5 has a tumor-suppressive effect in clear cell renal cell carcinoma." (PMID 38584203, 2024).
colitis (4 papers, 2017 to 2025). Inflammation of the colon. "The deletion of Prmt5 results in ISCs deficiency, ectopic localization of Paneth cells, and spontaneous colitis." (PMID 39907873, 2025). "Colitis was associated with increased local PRMT5 expression, which was inhibited by AMI-1 treatment." (PMID 28588584, 2017). "PRMT5 expression increased during experimental inflammation colitis and significantly decreased after the AMI-1 treatment." (PMID 28588584, 2017). "Colitis was associated with increased local PRMT5 expression, and AMI-1 treatment significantly decreased the PRMT5 expression." (PMID 28588584, 2017). "Once colitis developed, the mice were intravenously injected with 5 × 105 PRMT5 knockdowns or control CD45.1+ Tregs or with the same number of CD45.2+ naïve T cells and followed for 3 weeks." (PMID 28588584, 2017). "Also, the protective role of the PRMT inhibitor was analogy in PRMT5 knockdown Tregs by relieving colitis." (PMID 28588584, 2017). "In the murine model of C. rodentium infection-induced colitis, which shares the epithelial barrier dysfunction and inflammation evident in human IBD, Prmt5 was similarly up-regulated." (PMID 37666668, 2023).
esophageal cancer (4 papers, 2018 to 2021). A primary or metastatic malignant neoplasm involving the esophagus. "Interestingly, in conditions, especially in esophageal cancer, where PRMT5 is not up-regulated but FAM47E was significantly up-regulated, substantial proportion of targets positively regulated by PRMT5 were also significantly up-regulated." (PMID 33376131, 2021).
experimental autoimmune encephalomyelitis (4 papers, 2020 to 2023). An autoimmune demyelinating disease of the central nervous system that is produced experimentally in animals by the injection of homogenized brain or spinal cord in Freund's adjuvant. "To determine whether PRMT5 and PRMT5-dependent CyclinE1 activity is linked to active clinical signs, we used the SJL experimental autoimmune encephalomyelitis (EAE) model of MS." (PMID 34168658, 2021). "Prmt5 inhibition or deletion in CD4+ T cells has been reported to ameliorate experimental autoimmune encephalomyelitis (EAE), but the detailed molecular mechanisms have not yet been elucidated." (PMID 37533053, 2023).
lung squamous cell carcinoma (4 papers, 2013 to 2025). "Our study identified that within NSCLC, both cytoplasmic and nuclear PRMT5 expression was more frequent in squamous cell carcinomas than in adenocarcinomas, which is in line with prior observations that DNA methylation is universal phenomenon in lung squamous cell carcinomas." (PMID 24326178, 2013).
oral squamous cell carcinoma (4 papers, 2020 to 2024). "Recently, PRMT5 has been claimed as an activator of EMT in oral squamous cell carcinoma, and this could be a mechanism of PRMT5-mediated cancer invasion and metastasis." (PMID 33060569, 2020). "In this study, the genomics data for the PRMT5 and APE1 genes, including their expression, CNVs, and clinical outcomes, were analyzed using TCGA’s data set for oral squamous cell carcinoma patients." (PMID 37887269, 2023).
sarcoma (4 papers, 2023 to 2025). A usually aggressive malignant neoplasm of the soft tissue or bone. "As a first indicator for a potential relevance of PRMT1 and PRMT5 in ES, we queried the R2 platform for PRMT1 and PRMT5 mRNA expression focusing on the Filion dataset which includes ES alongside other fusion-positive sarcomas." (PMID 40823091, 2025). "Among all 355 patients enrolled in the phase I studies investigating PRMT5 inhibitors, only 5 presented with a sarcoma, and 2 of these patients achieved long-term disease stabilization (>6 months)." (PMID 37861293, 2023). "By analyzing two large independent datasets, we show that PRMT5 overexpression is also associated with an increased risk of metastasis and adverse outcomes in patients with STS, suggesting important roles in sarcoma tumorigenesis and a potential role as a therapeutic target." (PMID 37861293, 2023). "The efficacy of PRMT5 inhibitors in the context of MTAP passenger deletions has been demonstrated in several cancers, suggesting that patients with FUS/EWSR1-TFCP2 sarcoma and CDKN2A/MTAP loss may also benefit from PRMT5 inhibitors, which are currently being tested in clinical trials." (PMID 38168093, 2024). "Therefore, PRMT5 inhibitors and antifolate drugs may be potential therapeutic options to pursue in TFCP2 fusion sarcomas with MTAP deletion." (PMID 40361368, 2025). "Finally, our findings suggest that patients with TFCP2-rearranged sarcomas, which are refractory to conventional chemotherapy, may benefit from combination treatments that include platinum derivatives, ALK inhibitors, and, in the case of CDKN2A/MTAP co-deletions, drugs targeting PRMT5." (PMID 38168093, 2024).
ulcerative colitis (4 papers, 2017 to 2025). An inflammatory bowel disease involving the mucosal surface of the large intestine and rectum. "Correspondingly, the upregulation of PRMT1 and PRMT5 expression also accompanied bowel inflammation in patients with Crohn’s disease and ulcerative colitis." (PMID 32932854, 2020).
viral infection (4 papers, 2014 to 2023). "Our group has previously reported that PRMT5 protein levels are dysregulated during HTLV-1-mediated T-cell transformation as soon as 1 week after viral infection, suggesting that this cellular factor may be critical for the transformation of HTLV-1-infected T-cells." (PMID 36819050, 2023). "The study identified R124 residue as the direct catalyzing site by PRMT5; cGAS(R124K) mutant abolished PRMT5-mediated suppression of type I IFN production during virus infection." (PMID 36591232, 2022). "It recruits protein arginine methyltransferase 5 (Prmt5), facilitating IRF3 access upon viral infection." (PMID 36362045, 2022).
bladder urothelial cancer (3 papers, 2019 to 2022). "We used bioinformatics analysis to investigate PRMT5 overexpression in bladder urothelial cancer (BUC) and its clinical significance." (PMID 32392182, 2020). "PRMT5 circular RNA induced the epithelial-mesenchymal transition of bladder urothelial carcinoma through spongy miR-30c to promote its metastasis." (PMID 31857500, 2019).
dilated cardiomyopathy (3 papers, 2024 to 2025). Cardiomyopathy which is characterized by dilation and contractile dysfunction of the left and right ventricles. "A previous study also reported on the function of PRMT5 in cardiomyocytes, finding that conditional knockout of PRMT5 in cardiomyocytes caused dilated cardiomyopathy through dysregulation of protein O-GlcNAcylation, suggesting that PRMT5 maintains cardiac homeostasis." (PMID 38503742, 2024). "In the heart, our previous work identified Oga as a key target of PRMT5, linking its splicing regulation to cardiac homeostasis and protection against dilated cardiomyopathy." (PMID 40076920, 2025). "In the heart, PRMT5 regulates the RNA splicing of the O-GlcNAcase (Oga) gene, and its dysfunction results in elevated levels of protein O-GlcNAcylation, contributing to the development of dilated cardiomyopathy." (PMID 40076920, 2025). "Cardiac-specific Prmt5 knockout results in a pathological condition of dilated cardiomyopathy without induction of pathological conditions in adult mice." (PMID 40619438, 2025).
head and neck cancer (3 papers, 2017 to 2024). A primary or metastatic malignant neoplasm affecting the head and neck. "We observed coincidental high expression of E2F1 and PRMT5 in several tumour types, including pancreatic, colon, and head and neck cancer, with low expression in normal tissue." (PMID 32709847, 2020). "To examine the effect of IL-6 on PRMT5 nuclear localization, we performed nuclear/cytosolic fractionation and immunofluorescence staining experiments using head and neck cancer cell lines." (PMID 28107179, 2017). "In our mechanistic experiments, IL-6 treatment markedly enhanced nuclear translocation of PRMT5 in head and neck cancer cells." (PMID 28107179, 2017). "This suggests that PRMT5 may influence the progression of head and neck cancer by regulating ferroptosis." (PMID 38663941, 2024). "However, very little is known about the expression and biological role of PRMT5 in head and neck cancer." (PMID 28107179, 2017). "Inhibitors designed to block PRMT5 nuclear translocation and its transcriptional regulatory function may lead to the development of novel therapeutic strategies for the treatment of head and neck cancer." (PMID 28107179, 2017). "Indeed, our mechanistic experiments showed that IL-6 treatment of head and neck cancer cells promote PRMT5 translocation to nucleus." (PMID 28107179, 2017). "However, there is no reported study that has examined PRMT5 expression, particularly subcellular localization, in a large cohort of tumors from head and neck cancer patient population and its correlation with patient outcome." (PMID 28107179, 2017).
Hepatic steatosis (3 papers, 2020 to 2025). Steatosis is a term used to denote lipid accumulation within hepatocytes. "A previous study showed PRMT5 promoted the development of hepatic steatosis under a high-fat diet by facilitating the suppression of transcription regulators in mitochondrial biogenesis such as PPARα." (PMID 37834101, 2023). "Collectively, the gene expression profiling results suggest that Prmt5 knockout causes defects in fatty acid metabolic pathways in WAT, leading to elevated serum lipids and hepatic steatosis." (PMID 33304767, 2020). "Additionally, Prmt5 AKO promotes cholesterol biogenesis, associated with hyperlipidemia and hepatic steatosis in mice." (PMID 41648662, 2025). "This, in turn, elevated mitochondrial and peroxisomal fatty acid oxidation, demonstrating a propensity to slow down the development of fatty liver, although the mechanism with which PRMT5 regulates AKT phosphorylation remains unclear." (PMID 37834101, 2023).
Hodgkins lymphoma (3 papers, 2012 to 2021). A heterogeneous group of malignant lymphoid neoplasms of B-cell origin characterized histologically by the presence of Hodgkin and Reed-Sternberg (HRS) cells in the vast majority of cases. "Influence of EBV status: comparison of immunohistochemical staining for PRMT1, CARM1 and PRMT5 in nodular sclerosis and mixed cellularity HL." (PMID 25436604, 2012). "A factor repressed upon PRMT5 inhibition, is the Basic Leucine Zipper ATF-like Transcription Factor, BATF3, which was shown to be required for proliferation in Hodgkin lymphoma, anaplastic large cell lymphoma as well as adult T cell leukemia/ lymphoma." (PMID 32555249, 2020). "We have recently reported that elevated levels of PRMT5 up‐regulates WNT/β‐CATENIN proliferative signalling through transcriptional repression of pathway antagonists, AXIN2 and WIF1, in three different types of non‐Hodgkin’s lymphoma cells." (PMID 33462997, 2021).
lung disease (3 papers, 2024 to 2026). "PRMT5 is implicated in endothelial inflammation and lung diseases, but its role in sepsis-associated lung injury remains unclear." (PMID 41568710, 2026). "The association between the anti-PRMT5 antibodies and RA-ILD identified in our study provides additional support for the role of autoantibodies in RA-associated lung disease." (PMID 40790333, 2025). "We then validated the prevalence of antibodies against PRMT5 in the sera of patients with SSc and demonstrated the close correlations of anti-PRMT5 antibodies with the progression or regression trajectories of skin and lung disease in SSc." (PMID 38684324, 2024). "Besides, anti-PRMT5 antibodies demonstrated promising predictive value for the progression of skin and lung disease in SSc." (PMID 38684324, 2024).
lung fibrosis (3 papers, 2024 to 2025). "Skin fibrosis and lung fibrosis were examined histopathologically 8 weeks after initiation of PRMT5 treatment." (PMID 38684324, 2024). "Interestingly, immunization of mice with PRMT5 and consequent anti-PRMT5 autoantibody production was shown to induce skin and lung fibrosis." (PMID 39046085, 2025). "Likewise, patients having experienced progression in lung fibrosis, determined by an increased involvement of semiquantified areas in high-resolution CT (HRCT) in the past 12 months, demonstrated a significant elevation in anti-PRMT5 antibody levels." (PMID 38684324, 2024).
lung NETs (3 papers, 2013 to 2022). "The nuclear overexpression of protein arginine methyltransferase-5 (PRMT5) was negatively associated with tumor grade, thus reflecting potential differences in the epigenetic control of oncogenesis of low- and high-grade lung NETs." (PMID 35158788, 2022).
lymph node metastasis (3 papers, 2020 to 2025). "The results indicated that the high PRMT5 expression in RCC patients was significantly linked to a tumor size greater than 7 cm (P = 0.002), a greater invasion depth (P < 0.001), lymph node metastasis (P = 0.005), and distant metastasis (P < 0.001)." (PMID 40756764, 2025). "The Kaplan-Meier curves also demonstrate poorer overall survival of patients with high PRMT5 expression, compared with those with low expression, with MIBC (T2-4) (P = 0.0360), absence of lymph node metastasis (P = 0.0298), and high-grade tumors (P = 0.0426)." (PMID 32392182, 2020).
male infertility (3 papers, 2019 to 2023). The inability of the male to effect fertilization of an ovum after a specified period of unprotected intercourse. "Another study also demonstrated that the spermatogonia-specific deletion of Prmt5 leads to germ cell loss and male infertility." (PMID 37834450, 2023). "In the present study, we observed that PRMT5 is abundantly expressed in spermatogonial stem cells (SSCs) and that Prmt5 deletion results in a progressive loss of SSCs and male infertility." (PMID 34113620, 2021). "In the present study, we demonstrated that the deletion of Prmt5 in germ cells resulted in loss of spermatogonial stem cells (SSCs) and male infertility." (PMID 34113620, 2021). "The results of our previous study demonstrated that inactivation of Prmt5 in male germ cells using Stra8-Cre causes aberrant spermatogenesis and male infertility, suggesting that PRMT5 is essential for the development of male germ cells." (PMID 34113620, 2021). "The results of our previous study revealed that the postnatal knockout of Prmt5 in male germ cells using Stra8-Cre led to defects in meiosis and male infertility." (PMID 34113620, 2021). "Conditional knockout of PRMT5 mediated by Blimp1-Cre in PGCs results in male infertility due to decreased repressive H2A/H4R3me2s marks on TEs and subsequent TEs activation." (PMID 31624244, 2019).
nasopharyngeal carcinoma (3 papers, 2022 to 2026). A carcinoma arising from the nasopharyngeal epithelium. "We demonstrate that PRMT5 facilitated paclitaxel resistance by inducing KCNMB4 expression in nasopharyngeal carcinoma cells." (PMID 41513606, 2026). "Here, we report that PRMT5 bound to EphA2, catalyzed the dimethylation of EphA2 at arginine 816, and then stabilized EphA2 via inhibiting Cbl-mediated EphA2 ubiquitination and degradation in nasopharyngeal carcinoma (NPC) cells." (PMID 41930341, 2026). "Importantly, targeting PRMT5 significantly sensitized nasopharyngeal carcinoma cells to paclitaxel both in vitro and in vivo." (PMID 41513606, 2026).